CEACAM6 (CEA cell adhesion molecule 6)
Diseases named in the same sentence as CEACAM6 in open-access papers (continued):
Sharing a sentence is not in itself a finding about the gene and the disease.
tumor (continued). "Consequently, the tumor suppressing effects of the immune response are weakened, while the tumor promoting effects of CEACAM6 significantly increase, resulting in poor OS in patients with advanced-stage GC." (PMID 28883649, 2017). "Scattered CEACAM6-positive tumor cells and tumor mass in adjacent tissues may be the consequence of invasion of strongly CEACAM6-positive tumors." (PMID 28883649, 2017). "Moreover, the present study provided new insights into the multiplicity and diversity of CEACAM6 expression and their potential functions in tumor development and progression." (PMID 29137373, 2017). "Network analysis of downstream gene signatures of CEACAM6 discovered several hub genes which may play critical roles in mediating tumor proliferation and metastasis." (PMID 29137373, 2017). "However, when CEACAM6 was used to differentiate intrahepatic tumor from benign disease, the AUC was 0.663." (PMID 26974538, 2016). "The 5G2 signal preferentially co-localized with CEACAM6 at the invasive front of the C48 tumour." (PMID 27098764, 2016). "Some CEA family members such as CEACAM6 may adhere to and inhibit tumor-infiltrating cytotoxic T cells." (PMID 25832000, 2015). "We used AP11 to analyze CEACAM6 expression by immunohistochemistry in 282 human tumor tissues." (PMID 25427744, 2015). "As expected, significant negative correlation was observed between CEACAM6 and E-cadherin, and E-cadherin expression was associated with depth of tumor invasion, lymph node metastasis and TNM stage in GC tissues." (PMID 25398131, 2014). "Similarly, 8 of the 9 low PDEF expressing tumors showed low levels of CEACAM6 expression (tumors # 10-18, except tumor #12)." (PMID 23592399, 2013). "Secondly, the elevated CEACAM6 expression on tumor cells may increase intercellular interactions between tumor cells (since CEACAM6 is a cell adhesion molecule), leading to their increased adhesion and the formation of cellular aggregates." (PMID 23592399, 2013). "Strong cell surface expression of CEACAM6 was observed in CEACAM6-high tumor." (PMID 23592399, 2013). "Finally, we show that foci of CEACAM6 expressing cells are selectively ablated by treatment of xenotransplant tumours with pharmacological inhibitors of PI3K/AKT in vivo." (PMID 23021083, 2012). "Moreover, we show that over-expression of CEACAM6 increases tumour growth and tumour initiating activity by suppressing PI3K/AKT-dependent apoptosis of HNSCC in a xenotransplant model of HNSCC." (PMID 23021083, 2012). "Finally, our studies indicate that foci of CEACAM6 expressing cells are selectively ablated by treatment of xenotransplant tumours with pharmacological inhibitors of PI3K/AKT in vivo." (PMID 23021083, 2012). "Secondly, examining global expression of CEACAM6, at a tissue level, is not a good indicator of the presence or abundance of CEACAM6+ve foci/clonal variants within cell cultures or tumours." (PMID 23021083, 2012). "Next, we investigated whether reducing CEACAM6 expression would also be able to modulate tumour initiation and growth in the Detroit 562 cell line." (PMID 23021083, 2012). "The expression of CEACAM6 also correlates with the metastatic potential of some epithelial malignancies, suggesting that the altered expression of CEACAM6 may contribute to tumour progression." (PMID 23021083, 2012). "In addition, CEACAM6 over-expression also contributes in part, or wholly, to the increased tumour growth in a xenotransplant model of HNSCC." (PMID 23021083, 2012). "Therefore, we used the Detroit 562 cell line to examine the contribution of CEACAM6 to tumour initiating activity and/or tumour growth." (PMID 23021083, 2012). "Functional investigation of CEACAM6, involving over-expression and knock down studies, demonstrated that CEACAM6 over-expression could enhance tumour initiating activity and tumour growth via activation of AKT and suppression of caspase-3 mediated cell death." (PMID 23021083, 2012).
tumor (continued). "Thus, CEACAM6 likely represents one factor, of many, that can modulate tumour growth and tumour initiating activity." (PMID 23021083, 2012). "Finally, our studies show that CEACAM6+ve tumours, or tumour foci, are selectively sensitive to treatment with pharmacological inhibitors of PI3K/AKT in vivo." (PMID 23021083, 2012). "However, it should be noted that the percentage area positive for CEACAM6 varied from approximately 60% down to 0% between individual tumours." (PMID 23021083, 2012). "For all tumor cores evaluated, the amount of CEACAM6 was greater than that of CEACAM5." (PMID 17201906, 2007). "With growing knowledge of the effects of CEACAM5 and CEACAM6 on tumour biology, novel therapeutic strategies that focus more on perturbing the tumorigenic functions of these antigens may now be indicated." (PMID 17576469, 2007). "However, the results in this study are the first to explore differences in both CEACAM5 and CEACAM6 as a function of tumor histotype across six tumor tissues." (PMID 17201906, 2007). "In this work, we evaluated CEACAM5 and CEACAM6 as a function of tumor cell differentiation." (PMID 17201906, 2007). "Silencing of the CEACAM6 gene impairs metastasis and suppresses tumor growth." (PMID 16868542, 2006). "Of all biomarkers CEA mRNA was expressed at the highest levels in tumours followed by CEACAM6." (PMID 16755296, 2006). "However, it has been claimed that tumour levels are higher for CEACAM6 than CEA and that CEACAM6 therefore would be the better tumour marker." (PMID 16755296, 2006). "This was due to CEA that, contrary to expectation, had higher expression level in tumour cells than CEACAM6 and that CEACAM6 was expressed in myeloid immune cells with the risk that tumour cells expressing fairly low levels of this marker would drown in the immune cell background of the node." (PMID 16755296, 2006). "CEACAM6 could promote angiogenesis/metastasis and suppress anti-tumor immunity." (PMID 41640009, 2026). "In addition, single-cell sequencing and spatial immune profiling could help clarify how CEACAM6 influences the tumor immune microenvironment." (PMID 40936892, 2025). "Additionally, it could not be determined in this study whether plasma CEACAM6 levels were a surrogate for tumor CEACAM6 expression or a biomarker for efficacy." (PMID 40860822, 2025). "Therefore, both siCEACAM6 and miR-29a may act as tumor suppressors in PDAC by inhibiting CEACAM6 expression." (PMID 40282889, 2025). "Neither CEACAM5 nor CEACAM6 have previously been linked to resistance to tumor acidity." (PMID 38502695, 2024). "Furthermore, we show that CEACAM6 is highly expressed in samples from late-stage tumor patients." (PMID 38502695, 2024). "Cellular metabolism was not altered during model establishment, and no spontaneous tumor rejection was observed in the control arms of our in vivo experiments, showing that no undue immunogenicity was caused by the expression of the human CEACAM6 protein." (PMID 38398062, 2024). "CEACAM6 may offer a means of improving drug delivery specifically to acidic tumor regions." (PMID 38502695, 2024). "In addition, CEACAM6 might also be involved in key cellular events such as tumor migration and invasion in GGN through adhesion." (PMID 37745301, 2023). "This study suggests that NEO-201 could be a good anti-glycan mAb for the treatment of different types of cancers not only expressing core 1 and/or extended core 1 O-glycans attached to the tumor-associated variant of CEACAM5 and CEACAM6 but also to other tumor-associated proteins." (PMID 36291783, 2022). "Future multi-institutional study of matched human tumor tissue (primary lung, solid parenchymal brain metastases, and LM), and genetically modifiable in vivo mouse models of LM, will allow us to further determine how and under what treatment pressure CEACAM6 promotes brain-trophic metastases." (PMID 34625644, 2021).
tumor (continued). "In addition, MUC2 downregulation has been associated with increased expression of tumor-associated antigen carcinoembryonic antigen-related cell adhesion molecules 5 and 6 (CEACAM5 and CEACAM6), which are involved in cell adhesion, migration, tumor invasion, and metastasis." (PMID 29967641, 2018). "CEACAM6 may be a better tumor marker than CEA for predicting the OS of patients with GC." (PMID 28883649, 2017). "In addition, CEACAM6 increases tumor cell resistance to 5-FU." (PMID 28883649, 2017). "Thus, CEACAM6 was better than CEA as a tumor marker for predicting OS in patients with GC." (PMID 28883649, 2017). "This study aims to evaluate whether CEACAM6 can serve as a tumor marker using AP11." (PMID 25427744, 2015). "CEACAM1, CEACAM5 and CEACAM6 may be released from epithelial tumors in microvesicles, whereas tumor endothelia only contain CEACAM1 which has a receptor function for other CEACAMs, influences T cell behavior and regulates the tumor matrix and microvascularization." (PMID 25832000, 2015). "The focal expression of CEACAM6 in tumours derived from the Detroit 562 cell line was consistent with our earlier study reporting that clonal variants existed within the parental Detroit 562 cell line that could be discriminated based on variant-specific transcriptomic signatures." (PMID 23021083, 2012). "Moreover, HNSCC patient tumours demonstrated focal expression of CEACAM6." (PMID 23021083, 2012). "Notably, expression of the tumour marker Ceacam6 and Cdcp1 were upregulated as was prostaglandin synthase 2 (Ptgs2) that might lead to a modified arachidonic acid metabolism pertinent to the respiratory epithelium." (PMID 21152443, 2010). "A decrease in SFTPA1 expression (an AT2 marker) was observed, whereas CEACAM6 and SPINK1 (CAS markers) exhibited high expression levels in tumour regions (GG and S) compared to the DN region." (PMID 40824728, 2025). "More importantly, SecTA expresses multiple molecules related to cell migration and adhesion, such as CEACAM6 and TM4SF1, which not only increase tumour cell invasiveness but also create conditions for distant metastasis." (PMID 40539065, 2025). "The expanding landscape of ADC targets in CRC now includes not only antigens on bulk tumor cells (CEACAM5, HER2), but also those on cancer stem cells (LGR5) and critical stromal components (CEACAM6), offering multiple avenues to dismantle the tumor ecosystem." (PMID 41256852, 2025). "This suggests that inhibition of CEACAM6 can inhibit the EMT process, thus achieving the purpose of inhibiting tumor metastasis and invasion." (PMID 38796667, 2024). "CSF CEACAM6 and HE4 level had the high possibility of clinical usefulness in monitoring tumor burden and clinical efficacy, and evaluating prognosis of LM patients." (PMID 38304432, 2024). "To test the synergetic effect of neutralizing tumor acidity with immunotherapy, we developed a pancreatic orthotopic murine tumor model (KPC961) expressing human CEACAM6." (PMID 38398062, 2024). "In line with the high expression of TRIM9, the protein level of CEACAM6, Smad2/3 and MMP2 were upregulated in TRIM9 overexpressed tumor tissues." (PMID 37249822, 2023). "All tumor cells showed high expression in signature genes of pancreatic epithelial lesion, like KRT19, MUC1, EPCAM and CEACAM6." (PMID 37007745, 2023). "Both CEACAM6 and CTSG were downregulated in this study, which indicated the importance of CEACAM6 and CTSG in tumor recurrence in HCC patients after LT." (PMID 37089051, 2023). "Targeted assays measuring CEACAM6 transcript abundance in blood may be of potential utility for the management of patients with diseases presenting with systemic inflammation and for the management of patients with cancer, where the assay could potentially be run both on blood and tumor tissues." (PMID 39239252, 2022).
tumor (continued). "However, CEACAM6 presents with the distinct advantage of also being of potential value in the management of patients with cancer, whether the assay would be used to measure transcript abundance in blood or in tumor tissues." (PMID 39239252, 2022). "The mAb NEO-201 with selective CEACAM5 and CEACAM6 targeting capacity and anti-tumour activity showed strong immunoreactivity in a cohort of MOC samples and other tumour types with minimal cross-reactivity to surrounding normal tissue." (PMID 34830751, 2021). "The more dependent CA19-9 significantly correlated with the same parameters as CEACAM6 and CEA, but also with the parameters N and tumour diameter." (PMID 34207784, 2021). "We identified five classes of tumor cells (C8, C9, C10, C18, C20), which expressed the tumor cell marker genes EPCAM, CEACAM6, or MKI67." (PMID 32580738, 2020). "Part of them have been documented to be tumor promoter genes of PC, such as GABRP, CEACAM5, CEACAM6 and CST1." (PMID 31706267, 2019). "A CRISPR/Cas9 Knockout (KO) of CEACAM6 in PDA cell line for quantitative proteomics, mitochondrial bioenergetics and tumor growth in mice were conducted." (PMID 31797958, 2019). "The 5G2 signal was also more predominant on the apical membrane and inside the lumen in patient tumours similar to CTOSs-derived xenotumours compared to the CEACAM5 and CEACAM6 signal." (PMID 27098764, 2016). "We examined the expression of CEACAM6 with AP11 in 11 human carcinoma cell lines by flow cytometry and 439 human tissues including 282 tumor tissues and 157 normal tissues by immunohistochemistry." (PMID 25427744, 2015). "These genes included tumor markers (MUC16), genes that control tumor migration (MYL9), metastasis (CEACAM6, VEGFC, CX3CL1, CST1, CCL5, S100A9, IGF1, NOTCH3), cell adhesion (FN1, CEACAM1), and inflammation (TRAF2, NF-κB2 and RelB)." (PMID 26090868, 2015). "Silencing of genes with reported immune-regulatory function, namely PD-L1, CEACAM-6, and galectin-3 (GAL-3), strongly reduced luciferase activity only in the cytotoxicity setup, whereby PD-L1 showed a higher impact on tumor lysis." (PMID 25691366, 2015). "CEACAM6-mediated inhibition of apoptosis in vivo therefore contributes in part, or wholly, to the ability of HNSCC cells to initiate a tumour in a xenotransplant model of HNSCC." (PMID 23021083, 2012). "CEACAM6 is i) overexpressed focally in SCC, ii) overexpressed in SCC cell lines and iii) CEACAM6 expression level correlates with tumour initiating activity." (PMID 23021083, 2012). "CEACAM6 expression was examined in normal squamous epithelia as well as a number of patient HNSCC samples and tumours derived from HNSCC cell lines injected into NOD/SCID mice." (PMID 23021083, 2012). "Emerging, clinical and molecular data unequivocally show that the presence of intratumoural heterogeneity, exemplified by focal CEACAM6 overexpression in HNSCC cells, is a major contributor to tumour drug responses and patient outcomes." (PMID 23021083, 2012). "In a study recently published, basal-like tumour cell lines were characterized by the concomitant hypermethylation of a six gene panel (CDH1, CEACAM6, CST6, ESR1, LCN2, SCNN1A)." (PMID 20338046, 2010). "For all tumors, the amount of CEACAM6 expressed was greater than that of CEACAM5, and reflected tumor histotype." (PMID 17201906, 2007). "First, although CEACAM6 has been reported to be associated with epithelial–mesenchymal transition and anoikis resistance, we did not conduct additional analyses to determine whether the tumor reduction observed in our study was mediated through these mechanisms or other pathways." (PMID 40282889, 2025). "In this study, 89Zr‐Df‐Tinurilimab showed a high tumor uptake at around 17% ID g−1 and low uptake in other nontarget organs in CEACAM6‐positive models, providing excellent tumor contrast." (PMID 40178153, 2025). "CEACAM6 and HE4 in CSF are primarily derived from tumour cells." (PMID 40232301, 2025).
tumor (continued). "Collectively, these findings suggest that blockade of CEACAM6 may potentially remodel the TIME, thereby unleashing potent anti-tumor immunity." (PMID 39918687, 2025). "CEACAM6 and SLC2A1 may also play a role in IPMN tumor progression, with increased expression of these genes in high‐grade versus low‐ and intermediate‐grade IPMNs being previously observed." (PMID 39660530, 2024). "Our previous study has defined the CEACAM6 as a tumor biomarker for LM, but the control group were normal CSF samples from benign disease patients, not LUAD patients without LM (Wiot-LM)." (PMID 38304432, 2024). "Subclusters 4 and 5 may be related to tumor invasion and metastasis (migration factors CXCL3 and CXCL1; adhesion factors CEACAM6 and EMP1), suggesting that they may be tumor cell clusters with a greater degree of malignancy." (PMID 38927691, 2024). "Overall, the in vivo results were in accordance with the in vitro data showing that CEACAM6 decreased tumor cell adhesion to the pulmonal blood vessels but did not affect tumor cell viability." (PMID 39468006, 2024). "The results showed that CEACAM6 was highly expressed by only the tumor cells but not the adjacent normal tissues in vivo." (PMID 35484598, 2022). "In previous studies, we reported that the humanized IgG1 mAb NEO-201 reacts against numerous carcinomas expressing tumor-associated variants of CEACAM5 and CEACAM6, but it is not reactive against most normal epithelial tissues." (PMID 36291783, 2022). "Normal and tumour tissues from such patients were analysed by qRT-PCR for the following 12 genes; six from RNA-seq: CLDN1, MAGEB2, CD24, CEACAM6, IL1B and ISG15 and six from RNA-seq and proteomics cross-linking: AKR1C3, TNFAIP2, RAB7A, LGALS3BP, PSCA and SSRP1." (PMID 36428603, 2022). "Previously, we reported that NEO-201 binds to several tumors expressing tumor-associated CEACAM5 and CEACAM6 variants but does not bind to those expressed in healthy tissues." (PMID 36291783, 2022). "To confirm that NEO-201 binds specifically to cancer cells expressing tumor-associated variants of CEACAM-5 and CEACAM-6, which are not expressed in normal tissues, we used human tissue microarrays of various cancer types for immunohistochemistry analysis." (PMID 35804808, 2022). "Along with the trajectory, epithelial cell marker EPCAM and ductal marker KRT19 exhibited sustained high expression levels during PDAC progression, while genes previously reported to be involved in tumor progression, such as MUC1 and CEACAM6, gradually upregulated along with the transition." (PMID 34732701, 2021). "Other than REG family and dual oxidase genes, microarray analysis suggested that expression of CEACAM6 and CEACAM7, members of the carcinoembryonic antigen-related cell adhesion molecule family, and MUC1, which inhibits the anti-tumor immune response, was upregulated by more than twofold." (PMID 33483567, 2021). "It is possible that a difference in glycosylation pattern explains the specific binding of NEO-201 to specific tumor-associated CEACAM-5 and CEACAM-6 variants but not to those expressed on healthy tissues as shown by the immunohistochemistry analysis." (PMID 32637350, 2020). "We used the tumour-targeting properties of pHLIP and the potent binding affinity of the PNA to construct a tumour-targeted PNA delivery vector (pHLIP-PNA) by fusing pHLIP to the PNA form of an siRNA targeting CEACAM6 (hereafter siCEACAM6)." (PMID 31474761, 2019). "In addition, DCISCAF2cy markedly up-regulated expressions of carcinoembryonic antigen-related cell adhesion molecule 5 (CEACAM5; CAM5) and CEACAM6 (CAM6), tumor-promoting cell–cell adhesion molecules." (PMID 31331982, 2019). "In GC tissues, tumor cells that had dissociated from the matrix exhibited strong CEACAM6 staining and formed spheres without apoptosis." (PMID 28883649, 2017). "CEACAM6 expression in tumor tissues was higher than that in matched non-tumorous tissues, consistent with our previous results." (PMID 25398131, 2014).